IL10 (interleukin 10)
Diseases named in the same sentence as IL10 in open-access papers (continued):
Sharing a sentence is not in itself a finding about the gene and the disease.
Cerebral ischemia (63 papers, 2010 to 2026). Restriction of arterial blood supply to the brain associated with insufficient oxygenation to support the metabolic requirements of the tissue. "Regarding tissue repair, ablation of Tregs promoted the worsening of infarcts in a brain ischemia model, and transfer of IL-10-deficient Tregs was ineffective in secondary prevention of infarct growth, suggesting the importance of Treg production of IL-10." (PMID 34417572, 2022). "High IL-10 levels tend to predict worse outcomes after hemorrhagic brain injury, whereas the converse is true for brain ischemia, low IL-10 levels resulting from SNPs increase the risk for IS and low levels after IS predict worse outcome." (PMID 28659854, 2017). "IL-10 overexpression is associated with a striking resistance to cerebral ischemia." (PMID 37196130, 2023). "In addition, a deficiency of IL-4 accompanied a lower expression of IL-10, which is an M2 microglia marker and a potent anti-inflammatory cytokine produced by microglia, in a cerebral ischemia–reperfusion animal model." (PMID 36181630, 2023). "HDACII inhibitory Tubastatin A has been used in cerebral ischemia; it has increased regulatory T cell (Treg) immunosuppressive ability and regulated interleukin-10 (IL-10) expression levels." (PMID 38178983, 2023). "Our results demonstrated that the expression of TNF-α, IL-6, and NF-κB p65 increased after reperfusion, while the expression of IκB-α and IL-10 decreased, suggesting that cerebral ischemia triggers inflammatory response." (PMID 36970418, 2023). "In animal models of cerebral ischemia, IL-10 significantly reduced infarct size and neurological deficits." (PMID 36970418, 2023). "Although in vitro and in vivo models of cerebral ischemia showed IL-10-mediated neuroprotective effects, the role of IL-10 in predicting clinical outcomes was unclear." (PMID 36530609, 2022). "TNF-α and IL-1β are classical inflammatory cytokines after cerebral ischemia, while IL-4 and IL-10 are anti-inflammatory cytokines." (PMID 35496902, 2022). "This study showed that AKG demonstrate a neuroprotective role in cerebral ischemia by promoting IL-10 protein." (PMID 35592527, 2022). "Low IL-4 has been shown to enhance excitatory transmission, thereby aggravating cerebral ischemia, and low IL-10 has been shown to exacerbate the inflammatory response after MCAo." (PMID 33924148, 2021). "Il-10 is an anti-inflammatory cytokine known to promote neuroprotection and mitigate the cytotoxic effects of neuroinflammation occurring after brain ischemia." (PMID 34360581, 2021). "We concluded that tFUS served as a unique technique to promote neurorehabilitation after brain ischemia by promoting microglia polarization and further regulating IL-10 signaling in the ischemic brain." (PMID 33532127, 2021). "Previous studies in animal models of cerebral ischemia have confirmed the role of IL-10 as a mediator of the protective effect mediated by Treg." (PMID 32111174, 2020). "Other studies conducted in animal models described beneficial effects of IL-10 administration both in brain ischemia and in PD." (PMID 32659950, 2020). "Different from the traditional view of the neuroprotective effect of IL-10, these findings broaden our understanding of the role of IL-10 in cerebral ischemia and provide empirical evidence for its therapeutic value." (PMID 31801113, 2019). "As a classic immunoregulatory cytokine, interleukin-10 (IL-10) can provide in vivo and in vitro neuroprotection respectively during cerebral ischemia and after the oxygen-glucose deprivation (OGD)-induced injury." (PMID 31801113, 2019). "As a traditional protective factor in cerebral ischemia, IL-10 has been found to suppress local inflammatory reactions and decrease neuronal damages in vivo and in vitro." (PMID 31801113, 2019). "Nevertheless, the study extends the understanding of the neuroprotective effect of IL-10 and suggests its potential therapeutic strategies against cerebral ischemia." (PMID 31801113, 2019).
Cerebral ischemia (continued). "In treating cerebral ischemia, an early administration of IL-10 can produce adverse effect and a later application in combination with NF-κB activator PMA is recommended." (PMID 31801113, 2019). "On the one hand, many studies show a special population of regulatory B lymphocytes secrete IL-10 and are protective in cerebral ischemia/reperfusion injury." (PMID 29807548, 2018). "IL-4 or IL-10 knock-out mice have a worse outcome after cerebral ischemia due to an enhanced expression of M2 markers." (PMID 30584250, 2018). "As a classic immunoregulatory and anti-inflammatory cytokine, interleukin-10 (IL-10) provides neuroprotection in cerebral ischemia in vivo or oxygen-glucose deprivation (OGD)-induced injury in vitro." (PMID 27456198, 2016). "Nevertheless, the study extends our understanding of the neuroprotective effect of IL-10 and suggests its therapeutic potential against cerebral ischemia." (PMID 27456198, 2016). "Previous studies demonstrated that IL-10 can protect neurons from injury by anti-inflammatory and anti-apoptosis after cerebral ischemia." (PMID 26366999, 2015). "Table I shows that cerebral ischemia/reperfusion significantly increased the levels of IL-1β and IL-10 in the serum." (PMID 25815894, 2015). "Nevertheless, the present study provides new molecular insight into the neuroprotective effect of IL-10 and suggests its possible therapeutic role in the management of brain ischemia." (PMID 26366999, 2015). "During cerebral ischemia and cerebral infarction, IL-10 facilitates recovery and the survival of injured neurons by alleviating inflammation and inhibiting neuronal apoptosis in areas of cerebral hemorrhage." (PMID 25587341, 2014). "Several studies have shown the neuroprotective effects of the administration of IL-10 in experimental models of cerebral ischemia." (PMID 23773291, 2013). "IL-10 was suggested to have important roles for neuronal protection in glutamate-mediated neuronal cell death, focal brain ischemia, and spinal cord injuries." (PMID 24278397, 2013). "GW0742 administration i.c.v. dose-dependently inhibited the increase of TNF-α, IL-1β, and IL-6 and the reduction of IL-10 in hippocampus of cerebral ischemia-reperfusion rat." (PMID 23056034, 2012). "Over-expression of IL10 in vivo markedly protected cortical tissue against cerebral ischemia using the IL10 transgene mice." (PMID 21490702, 2010). "IL-10 secretion from astrocytes induced by cerebral ischemia could exert an anti-apoptotic effect on injured neurons via the TLR2/NF-κB signaling pathway, which may improve learning and memory dysfunction after ischemic injury." (PMID 37196130, 2023). "In addition, in vitro experiments showed that miR-217 promotes the accumulation of histone deacetylase 5 (HDAC5) in the nucleus by targeting MEF2D, resulting in decreased expression of IL-10, thereby aggravating cognitive dysfunction after cerebral ischemia." (PMID 36399471, 2022). "The experiment suggested that IL-10 may function as a neuroprotective agent during cerebral ischemia/reperfusion." (PMID 35592527, 2022). "It was speculated that AKG suppressed cerebral ischemia-reperfusion injury and oxidative stress by promoting IL-10 expression." (PMID 35592527, 2022). "Moreover, Breg cell-mediated IL-10 production has been shown to limit tissue damage and improve recovery of function in a murine model of brain ischemia." (PMID 29467001, 2018). "Previous studies demonstrated that IL-10 increased after cerebral ischemia, and IL-10 overexpression could promote neurogenesis." (PMID 26441532, 2015). "This hypothesis is supported by previous reports showing activation of endogenous repair processes involving IL-10-mediated T-reg mobilization after cerebral ischemia." (PMID 26700169, 2015). "Whereas TNF-α and IL-1β appear to exacerbate cerebral injury, transforming growth factor-β and IL-10 may exert neuroprotective effects during cerebral ischemia reperfusion." (PMID 25092271, 2014).
Cerebral ischemia (continued). "Experimental results assessing the protective effects of ANP in a model of experimental cerebral ischemia in rats showed that it could not only decrease the cerebral water content, but also increase the serum levels of interleukin-10 (IL-10)." (PMID 25587341, 2014). "However, a later study using the rat model of cerebral ischemia demonstrated that the enhanced circulating level of IL‐10 was lowered by chronic treatment with l‐NAME." (PMID 24744897, 2014). "It is suggested that the protective effect of GZFLC on rat brain ischemia-reperfusion injury is partly due to its inhibition of proinflammatory cytokines IL-1β and TNFα and upregulated expressions of anti-inflammatory cytokines IL-10." (PMID 23818926, 2013). "Results showed that sevoflurane postconditioning can decrease serum tumor necrosis factor-alpha (TNF-α), interleukin-1 beta (IL-1β), nitric oxide (NO), nitric oxide synthase (NOS) and increase serum interleukin-10 (IL-10) levels in cerebral ischemia reperfusion rats." (PMID 22210172, 2011). "IL-10 is well known for its positive effects in cerebral ischemia in rats." (PMID 21192826, 2010). "Activation of NF-κB induces the production of pro-inflammatory cytokines (IL-4, IL-10, IL-13, TGF-β) and adhesion molecules (IL-6, IL-1β and ICAM-1), thus intensifying tissue injury in cerebral ischemia-reperfusion." (PMID 40656619, 2025). "Cerebral ischemia produces great amounts of proinflammatory factors such as TNF-α and IL-1β and inhibits the production of anti-inflammatory factors such as IL-10 and IL-449." (PMID 37132753, 2023). "The most important cytokines related to inflammation in cerebral ischemia include IL-1β, TNF-α, IL-6, IL-10, and transforming growth factor-β (TGF-β)." (PMID 35656190, 2022). "As pointed out in rat models of cerebral ischemia, treatment with TEL significantly decreased the pro-inflammatory cytokine levels and elevated the anti-inflammatory IL-10 levels." (PMID 35553009, 2022). "BC/GP also increased the expression of IL-10 and TGF-β to protect against neuronal injury after cerebral ischemia." (PMID 33891262, 2021). "In the striatum, we have shown that relative expression of Nt‐3, Nestin, β‐actin, Tnfα, Il‐1β, Il‐6, and Il‐10 increased whereas expression of Bdnf, Gdnf, Vegf, and β‐III tubulin decreased after cerebral ischemia." (PMID 32281225, 2020). "Our results demonstrated that administration of VAC extract ameliorates the deleterious effects of cerebral ischemia by reducing the infarct volume and sensory-motor disorder as well as MMP-9 level and increasing the serum level of IL-10." (PMID 31807255, 2019). "Anti-inflammation related genes Arginase 1 (Arg1) and Chitinase-like 3 (Ym1) peaked at D1 while IL-10, Transforming growth factor β (TGF-β) and CD206, which were induced at 1 day after cerebral ischemia, peaked by 7 to 14 days." (PMID 29896414, 2018). "The most important cytokines that are related to inflammation in cerebral ischemia are IL-1, TNF-α, IL-6, IL-10, and transforming growth factor-β (TGF-β)." (PMID 29540536, 2018). "Similar results were obtained from PEMF exposure after brain ischemia, which indicated that PEMF influences neuroinflammation via elevation of anti-inflammatory IL-10 and reduction of pro-apoptotic tumor necrosis factor." (PMID 28220060, 2017). "Brain ischemia and reperfusion did not affect the expression of IL-10, an anti-inflammatory cytokine, in the blood of old and young mice." (PMID 37697393, 2023). "It is possible that transplantation of RACs including EPCs and M2 macrophages contributes to microenvironmental regulation to induce IL-10-mediated antiinflammation and VEGF-mediated vascularization in brain ischemia, although further work will be needed to confirm this." (PMID 30682162, 2019). "Moreover, upregulation of IL-10 and the STAT3 pathway and downregulation of NFκB have been proposed as the mechanisms for improved outcomes following cerebral ischemia in mice that overexpress IL-32α." (PMID 28659854, 2017).
Cerebral ischemia (continued). "Cytokines that participate in the inflammation after cerebral ischemia include the neurotoxic cytokines interleukin-1β (IL-1β), tumor necrosis factor-alpha (TNF-α), neuroprotective cytokines interleukin-6 (IL-6), interleukin-10 (IL-10) and transforming growth factor-β." (PMID 21740583, 2011). "In a diabetic rat model of cerebral ischemia–reperfusion, administration of Res at a dose of 20 mg/kg effectively reduced levels of malondialdehyde (MDA), TNF-α, IL-6 and myeloperoxidase (MPO), while increasing levels of catalase (CAT), superoxide dismutase (SOD), and IL-10." (PMID 41601537, 2026). "However, our study was limited in that changes of intracellular calcium after cerebral ischemia as well as the expression of IL-10, and the other anti-inflammatory factors were not examined." (PMID 34943061, 2021). "After brain ischemia, levels of the pro-inflammatory IL-1β and TNF-α were elevated in the MCAo + vehicle group (155% and 187% of sham control levels, respectively), whereas anti-inflammatory IL-10 levels were not significantly changed (88% of sham values)." (PMID 35631536, 2022).
fungal infections (63 papers, 2008 to 2025). "Specifically, the rs1800896 SNP, located in the promoter region of the gene encoding the immunoregulatory cytokine IL-10, has been found to promote increased levels of secreted IL-10 following fungal infection in vitro." (PMID 38651925, 2024). "Based on these premises, the current study shows the potential of detecting Aspergillus-specific T cells producing IL-10 to diagnose IA in a large series of hematologic patients at high-risk for invasive fungal infections." (PMID 38980880, 2024). "SNPs in cytokine coding genes influence the low production of TNFα, IFNγ, and IL-10, and it was observed that these variations make the Caucasian population susceptible to fungal infections." (PMID 34490039, 2021). "Genetic variation in IL-10 has also been found to be the underlying cause of susceptibility toward fungal infections like IA." (PMID 34490039, 2021). "Mice experimentally infected presented high IL-10 which was associated with the apoptotic process induced by the fungal infection." (PMID 27622513, 2016). "Also in our in vivo data at the onset of infection and at progression the immune response to invasive fungal infection is polarized towards the production of IL-10, while the resolution of infection is associated with increasing IFN-γ production." (PMID 38980880, 2024). "Elevated levels of IL-10 have been associated with uncontrolled fungal infections." (PMID 38115055, 2023). "It is known that mice deficient in IL-10 more susceptible to fungal infection." (PMID 32801570, 2020). "Increased IL-10 values are related to fungal infection susceptibility and led us to speculate that infection may be established through suppression of the host immune response." (PMID 28542438, 2017). "If the IL-10 deficiency is a long-term one, it can be harmful as the excessive production of proinflammatory cytokines could cause septic shock during bacterial, viral and fungal infections." (PMID 37241135, 2023). "Therefore, the susceptibility to fungal infections after antibiotic use may be due to dysregulation of mucosal immune regulatory molecules such as IL10 and IgA." (PMID 36118040, 2022). "Also, IL-10 plays a decisive role in the development of immune paralysis, the development of temporary immunodeficiency after trauma, major surgery, burns, shock, and high-risk bacterial/fungal infections." (PMID 32582189, 2020). "Thus, high levels of IL-10 have been linked to susceptibility to fungal infections." (PMID 25360137, 2014). "While protection against fungal infections mainly requires the development of T helper (Th)-type of adaptive immunity, fungal susceptibility is mostly associated with the development of Th2-type responses or production of immunosuppressive cytokines, such as interleukin (IL)-10." (PMID 24205424, 2013). "Although several cell types contribute to the regulation of immune responses, regulatory T lymphocytes producing IL-10 (T reg), with tolerogenic activity, have been described in fungal infections of both mice and humans." (PMID 40214449, 2025). "Anti-inflammatory cytokines such as IL-3, IL-4, IL-5, IL-9, IL-10, and IL-13 were also induced within 3 h of fungal infection in all three groups of mice and remained high up to the 7th day period." (PMID 38783167, 2024). "The results further revealed significant differences in TNF-β, IL-12p70, IL-6, IL-8, and IL-10 between the pulmonary bacterial infection group and the fungal infection group (P < 0.05)." (PMID 36319826, 2022). "The highest increase was observed in the production of IL-10 by infected cells, confirming the important role of IL-10 in regulating the immune response to fungal infections." (PMID 36555687, 2022). "A previous observation from Roilides suggests that IL-10 affects the host PMN phagocytes that are involved in fungal defense, inhibiting PMN and fungi phagocyte activity, thus increasing fungal infection risk." (PMID 36443718, 2022).